INSM2 (INSM transcriptional repressor 2)
Description:
May function as a growth suppressor or tumor suppressor in liver cells and in certain neurons.
Synonyms: IA6; IA-6; Mlt1
Tractability: No criterion of Open Targets' tractability assessment is met for any kind of drug.
Gene: Protein-coding gene on chromosome 14 (35,534,164 to 35,537,054, forward strand). Ensembl gene ENSG00000168348.
Subcellular location: Cytoplasm; Nucleus
Subcellular location (Human Protein Atlas): Nucleoplasm
Gene Ontology:
Molecular function: DNA-binding transcription repressor activity, RNA polymerase II-specific; RNA polymerase II cis-regulatory region sequence-specific DNA binding; DNA-binding transcription factor activity
Biological process: negative regulation of transcription by RNA polymerase II; neuron differentiation; regulation of cell cycle process; cell differentiation
Cellular component: nucleus; transcription repressor complex; cytoplasm
Genetic constraint (gnomAD): Loss-of-function variants: 12 observed, 24.43 expected, observed/expected ratio (o/e) 0.49, 90% interval 0.31 to 0.8. The synonymous counts are far from expectation, so gnomAD's model fits this gene poorly and the ratio says little. Missense variants: 773 observed, 722.17 expected, observed/expected ratio (o/e) 1.07, 90% interval 1.01 to 1.14. Synonymous variants: 418 observed, 340.03 expected, observed/expected ratio (o/e) 1.23, 90% interval 1.13 to 1.33.
Homologues: Orthologues: chimpanzee INSM2 (99% identical), macaque INSM2 (96% identical), dog INSM2 (85% identical), rabbit INSM2 (81% identical), pig INSM2 (76% identical), rat Insm2 (65% identical), mouse Insm2 (65% identical), guinea pig INSM2 (63% identical), zebrafish INSM2 (42% identical), tropical clawed frog INSM2 (34% identical), Drosophila melanogaster nerfin-1 (22% identical), Caenorhabditis elegans egl-46 (17% identical). Paralogues in human: INSM1 (37% identical).
Diseases named in the same sentence as INSM2 in open-access papers:
INSM2 is named in the same sentence as 14 diseases in open-access papers, as found by Europe PMC text mining. Sharing a sentence is not in itself a finding about the gene and the disease. The quoted sentences say what the papers report.
neuroblastoma (6 papers, 2018 to 2025). Neuroblastoma (NB) is the most common solid, extracranial childhood tumor. "In conclusion, we speculate a mechanism model of Super-enhancer-associated INSM2 promoting the progression of neuroblastoma." (PMID 36114560, 2022). "INSM2 as a super-enhancer-associated gene could regulates lipid metabolism by modulating mTOR signaling pathway in neuroblastoma." (PMID 36114560, 2022). "INSM2 mediates the lipid metabolism SREBP1expression via the mTOR signaling pathway, which further interferes with lipid metabolism in neuroblastoma." (PMID 40636521, 2025). "Insm2 was shown to regulate insulin secretion in mice and lipid metabolism in neuroblastoma cell lines." (PMID 40362725, 2025). "We found that the expression of INSM2 in neuroblastoma was much higher than that in normal neural crest cells." (PMID 36114560, 2022). "Next, we compared the expression of INSM2 in human normal neural crest cells and four different neuroblastoma cohorts." (PMID 36114560, 2022). "In our study, INSM2 was a newly identified gene regulating lipid metabolism in neuroblastoma." (PMID 36114560, 2022). "Explicit decrease in intracellular lipid droplet content after knockdown of INSM2 in neuroblastoma." (PMID 36114560, 2022). "We then performed full quantitative lipomic analysis on human neuroblastoma cells to determine the types of lipids that change in NB cells after knocking down INSM2." (PMID 36114560, 2022). "Therefore, we conclude that INSM2 may be positively regulated by neuroblastoma cell growth." (PMID 36114560, 2022). "In summary, we suggest that INSM2 affects the expression of SREBP1 by regulating the mTOR signaling pathway, which in turn affects the lipid metabolism process of neuroblastoma cells." (PMID 36114560, 2022). "Mechanistically, INSM2 regulates the expression of SREBP1 by regulating the mTOR signaling pathway, which in turn affects lipid metabolism, thereby mediating the occurrence and development of neuroblastoma." (PMID 36114560, 2022). "We recently discovered that the insulinoma-associated 2 gene (INSM2) could regulate lipid metabolism in neuroblastoma (NB) and is improperly controlled by super enhancers, a mammalian genome region that has been shown to control the expression of NB cell identity genes." (PMID 36114560, 2022). "Further studies are needed to learn whether or not INSM2 plays a role in tumorigenesis and functions as a prognostic marker in neuroblastoma." (PMID 30359270, 2018).
diabetes (5 papers, 2011 to 2022). "Given the risk of non-alcoholic fatty liver disease in type 2 diabetes mellitus (see recent meta-analysis), it is worth noting whether the deletion of Insm2 in mice affects the hepatic lipid accumulation and thus attributes to the risk of type 2 diabetes." (PMID 30359270, 2018). "The pancreatic islets regulate glucose metabolism through secretion of islet hormones such as insulin and glucagon, and INSM2 is a direct target of Ngn3 and NeuroD1, two crucial transcriptional factors involved in human diabetes and pancreatic islet development." (PMID 32511227, 2020).
Glucose intolerance (2 papers, 2018 to 2020). Glucose intolerance (GI) can be defined as dysglycemia that comprises both prediabetes and diabetes. "Deletion of Insm2 in mice resulted in reduced insulin secretion and glucose intolerance." (PMID 32511227, 2020).
Insulinomas (1 paper, 2020). "INSM2 is also called Insulinoma-associated gene 6 (IA6); Insulinomas are rare neuroendocrine tumors of the pancreas that are usually sporadic, but may occur in association with multiple endocrine neoplasia type 1 (MEN1) syndrome)." (PMID 32511227, 2020).
type 2 diabetes (1 paper, 2018). "Whether Insm2−/− mice induce islet cell differentiation and proliferation defects and/or develop type 2 diabetes, further experiments under more challenging conditions, such as high-fat and high-sugar diet, are required to test this hypothesis." (PMID 30359270, 2018). "Furthermore, genetic analysis by GWAS in a cohort of Africa Americans with type 2 diabetes revealed a significant association of the disease to a SNP (rs1952392, MAF = 0.0188; P < 0.001) at the proximal promoter region of the human INSM2 gene (personal communication)." (PMID 30359270, 2018).
tumor (2 papers, 2018 to 2022). "All these suggest that INSM2 plays an important role in the regulation of lipid formation in tumor cells and is a key factor in tumorigenesis." (PMID 36114560, 2022). "When compared to controls, INSM2 knockdown significantly slowed tumor growth and reduced tumor volume." (PMID 36114560, 2022). "We retrieved INSM2 mRNA expression data from more than 40 tumor cell lines (data from CCLE) and found that NB had the highest INSM2 expression." (PMID 36114560, 2022). "To further assess whether INSM2 knockdown could suppress tumor growth in vivo, we conducted a nude mouse xenograft model by subcutaneous injection of INSM2 knockdown NB cells." (PMID 36114560, 2022). "In a cancer-related study, Insm2 was found to be methylated and silenced in liver tumors of SV40 T antigen transgenic mice, suggesting its role in tumor inhibition." (PMID 30359270, 2018).
INSM2 also shares sentences with these, for which no sentence is quoted: type 1 diabetes (8 papers); Autoimmunity (2); Autoimmune Addison’s disease (1); cancer (1); Infertility (1); multiple endocrine neoplasia type 1 (1); neuroendocrine tumors of the pancreas (1); non-alcoholic fatty liver disease (1).